BCAM (basal cell adhesion molecule (Lutheran blood group))
Diseases named in the same sentence as BCAM in open-access papers (continued):
Sharing a sentence is not in itself a finding about the gene and the disease.
cancer (15 papers, 2013 to 2025). A tumor composed of atypical neoplastic, often pleomorphic cells that invade other tissues. "Here, we aimed to assess the expression of the BCAM protein in several cancer types, with the potential to develop a standardized companion diagnostic assay for BCAM-targeted therapy." (PMID 39207605, 2024). "It is noteworthy that altered expression/function of BCAM has been implicated in a variety of human cancers." (PMID 35969606, 2022). "Dysregulated basal cell adhesion molecule (BCAM) gene is associated with poor prognosis in various cancers." (PMID 35941663, 2022). "Because compounds for cell surface and intracellular targets are becoming increasingly available, a prospective clinical study is needed to verify the involvement of Lu/BCAM-laminin associated pathways in anti-adhesion strategies in cancer therapies." (PMID 28841878, 2017). "Growing evidence has demonstrated the association of BCAM with different cancers." (PMID 35941663, 2022). "Previously studies have reported the importance of Lu/BCAM in the progression of several types of cancer, although the underlying mechanism remains unclear." (PMID 28841878, 2017). "The top three genes with the highest AUC values (ORAI3, BCAM, and ATP6V0A1) have been associated with cancer development." (PMID 38256136, 2024). "To investigate this potential, we evaluated BCAM expression patterns in 3114 patients from both discovery and validation cohorts, spanning seven cancer types, using quantitative immunofluorescence (QIF)." (PMID 39207605, 2024). "This versatility allows for the combination of BCAM-targeted ADCs with other therapeutic agents, providing a robust platform to tailor treatments for different BCAM-expressing cancer subtypes." (PMID 39207605, 2024). "Intriguingly, BCAM expression is significantly associated with a short OS of only two other cancers among the 39 entities in the PRECOG database (red bars), pointing to a specific role for BCAM in OC." (PMID 36647260, 2023). "Basal cell adhesion molecule (BCAM) is a laminin α5 (LAMA5) binding membrane‐bound protein with a putative role in cancer." (PMID 36647260, 2023). "The heterogeneity of BCAM expression among different solid tumors determined the differential regulation mechanism of BCAM in different types of cancer." (PMID 35941663, 2022). "Importantly, the lack of correlation between BCAM and PD-L1 expression across cancer types indicates BCAM as an alternative prognostic marker and therapeutic target for patients less likely to benefit from PD-1/PD-L1 inhibitors." (PMID 39207605, 2024). "Understanding BCAM’s unique contribution could offer new insights into cancer progression and the development of innovative therapeutic strategies." (PMID 39207605, 2024). "The combination of BCAM monoclonal antibodies with the potent cytotoxic effects of small molecule drugs in ADCs might have their potential as a promising category of cancer therapeutics through precise targeting." (PMID 39207605, 2024). "Our study supports for Lu/BCAM as a potential target for suppression of cancer malignancy." (PMID 28841878, 2017). "Furthermore, we examined the localization of Lu/BCAM in bladder cancer specimens and cancer cells in vitro." (PMID 28841878, 2017). "Nonetheless, the expression level of BCAM varies among the cancer cell lines." (PMID 24223164, 2013). "Furthermore, ADCs targeting BCAM could circumvent drug resistance mechanisms, as their unique delivery method ensures that cytotoxic agents reach cancer cells directly." (PMID 39207605, 2024). "Moreover, the prognostic importance of BCAM has been explored in these types of cancer." (PMID 39207605, 2024). "The source and potential functions of soluble BCAM in cancer are unknown." (PMID 36647260, 2023).
cancer (continued). "Given the known crucial role of apoptosis and SO in cancer development and progression, it is tempting to speculate that BCAM may link these two key processes not only physiologically during normal tissue development but also pathologically in certain disease conditions." (PMID 35969606, 2022). "However, the mechanisms by which BCAM functions in cancer are poorly understood." (PMID 35969606, 2022). "As BCAM is a constituents of EVs released by HGSC cells it is tantalizing to speculate that EVs may act as a intercellular bridge facilitating the interaction of cancer cells with mesothelial and/or endothelial cells as part of the metastatic process in OC." (PMID 31588238, 2019). "Consistent with our finding, individual cancer-specific EMT signature genes such as PDIA3, HLA-A, BCAM, B2M, LGALS3BP, and HLA-C were highly expressed in cancer cells from infiltrated and excluded TMEs." (PMID 38086828, 2023). "For the BCAM-low subgroup, pathways including “cytokine-cytokine receptor interaction,” “chemokine signaling pathway,” “cell adhesion molecules” and “antigen processing and presentation” were mostly enriched, which was a vital link of immune response and could potentially induce cancer." (PMID 35941663, 2022). "The role of BCAM in cancer progression is controversial and has not been addressed for OC to date, including the origin and potential function of soluble BCAM abundant in the OC microenvironment." (PMID 36647260, 2023). "In most cancer types, the lack of correlation between BCAM and PD-L1 expression patterns suggests that BCAM could serve as a therapeutic target for patients less likely to respond to anti-PD-1 and anti-PD-L1 therapies." (PMID 39207605, 2024).
hematological disorders (2 papers, 2024 to 2025). "Abnormal expression of Lu/BCAM has been implicated in the development of various blood disorders and tumors, highlighting its potential as a molecular marker for disease diagnosis and as a therapeutic target." (PMID 39000374, 2024). "It is conceivable that Lu/BCAM is involved differently in solid and liquid tumors or hematological disorders." (PMID 40332051, 2025). "Lu/BCAM was found to be involved in various diseases, including hematological disorders and tumors, suggesting its potential as a potential diagnostic molecular marker or therapeutic target." (PMID 39000374, 2024). "Lu/BCAM functions as a receptor for laminin, an extracellular matrix protein; plays an important role in regulating cell adhesion, motility, migration and invasion; and is involved in hematological diseases and tumors." (PMID 39000374, 2024).
BCAM also shares sentences with these, for which no sentence is quoted: atherosclerosis (1 paper); breast tumor (1); bronchopulmonary dysplasia (1); cervical cancer (1); clear cell renal cell carcinoma (1); Cognitive impairment (1); connective tissue disorder (1); coronary artery disease (1); dementia (1); diabetes mellitus type 2 (1); glioblastoma (1); hyperlipidemia (1); invasive ductal carcinoma (1); Multiple Myeloma (1); muscular disorders (1); muscular dystrophy (1); myeloproliferative disorder (1); non-alcoholic steatohepatitis (1); non-small cell lung carcinoma (1); periodontitis (1); prostate carcinoma (1); sarcopenia (1); skin cancer (1); thymoma (1); thyroid cancer (1); uroepithelial carcinoma (1); X-linked sideroblastic anemia (1).